FGF1 (fibroblast growth factor 1)
Diseases named in the same sentence as FGF1 in open-access papers (continued):
Sharing a sentence is not in itself a finding about the gene and the disease.
Nephropathy (7 papers, 2016 to 2023). A nonspecific term referring to disease or damage of the kidneys. "The present study has demonstrated a molecular interaction between VEGFA and FGF1, which serves a protective function in the progression of renal diseases." (PMID 37415174, 2023). "In the present study, we showed that treatment with an FGF1 variant with decreased mitogenic potency (FGF1ΔHBS) inhibited podocyte EMT, depletion, renal fibrosis, and preserved renal function in two nephropathy models." (PMID 34149434, 2021). "Both immunofluorescence and western blotting analyses showed that the protein expression of FGF1 was substantially decreased in mice with ADR-induced nephropathy, suggesting a potential correlation between the levels of FGF1 and renal function." (PMID 31189876, 2019). "Although the role of FGF-1 (acidic FGF (aFGF)) in renal disease is less studied, FGF-1 may be involved in inflammatory diseases, such as rheumatoid arthritis." (PMID 27331812, 2016). "The findings of this study indicate that NGR1 has the potential to mitigate kidney disease and exert regulatory effects on VEGFA, F2R, and FGF1." (PMID 37415174, 2023).
coronary heart disease (6 papers, 2012 to 2024). "FGF1, a member of the fibroblast growth factor family, is known to alleviate the myocardial ischemia and cardiac insufficiency caused by coronary heart disease by promoting angiogenesis." (PMID 34025437, 2021). "There were 12 angiogenesis-related targets of salidroside in coronary heart disease, among which FGF1 (r = 0.237, P = 2.597E-3), KDR (r = 0.172, P = 3.007E-2) and HIF1A (r = -0.211, P = 7.437E-3) were correlated with the coronary flow index (CFI), and salidroside docked well with them." (PMID 37308900, 2023). "Currently, there are still some clinical trials to be processed, for example, a clinical study of Kangfuxin (a clinically approved extract from Periplaneta americana) and FGF2 in promoting the healing of donor site and FGF1 for the treatment of coronary heart disease." (PMID 36102060, 2022). "Promising clinical results have been achieved, for example, using fibroblast growth factor-1 (FGF-1): FGF-1 is currently in NIH phase II clinical trials for the pro-angiogenic treatment of coronary heart disease (NCT00117936) and wound healing in diabetic foot ulcers (NCT00916292)." (PMID 23133616, 2012).
fibrosis (6 papers, 2016 to 2025). the formation of excess fibrous connective tissue in an organ or tissue in a reparative or reactive process. "Masson staining showed that the area of uterine fibrosis in the WT+FGF1 group was significantly lower than that in the model group, indicating that FGF1-SS hydrogel have a therapeutic effect on endometrial injury." (PMID 35480860, 2022). "Furthermore, increased FGF-1 expression can inhibit renal and cardiac fibrosis by regulating the expression of extracellular matrix components." (PMID 40709999, 2025).
hyperlipidemia (6 papers, 2012 to 2026). "It is unclear what the cause of this hyperlipidemia is, since the mutations in the M2 protein are surface inaccessible and do not affect receptor or heparin binding properties, and the overall thermostability of M2 is essentially equivalent to WT FGF-1." (PMID 23133616, 2012). "Taurin-up-regulated gene 1 (TUG1) knockdown prevents hyperlipidemia and atherosclerotic lesions through up-regulating the miR-133a expression which targets the fibroblast growth factor 1 (FGF1)." (PMID 34552965, 2021). "It was suggested that TUG1 promoted hyperlipidemia and inflammatory cytokines such as IL-6 and TNF-α by sponging miR-133a, which targeted the fibroblast growth factor 1 (FGF1) in ox-LDL-treated RAW264.7 cells." (PMID 32082313, 2020).
Hypoglycemia (6 papers, 2020 to 2026). A decreased concentration of glucose in the blood. "FGF1 showed a robust glucose homeostasis profile, lowed the plasma insulin of db/db mice and did not cause hypoglycaemia and changeable plasma glucagon after chronic administration." (PMID 32979037, 2020). "Importantly, none of the analyzed FGF1 variants induced the hypoglycemia often observed with many current antidiabetic drugs." (PMID 41520078, 2026). "In addition, a higher dose of FGF1 did not result in hypoglycemia in the diabetic mice." (PMID 35011683, 2021).
breast tumor (5 papers, 2004 to 2023). "In our study, FGF1 expression in breast tumors was positively associated with MBD." (PMID 37546410, 2023). "Moreover, a study by Bane and colleagues reported that BRCA2-associated breast tumors are characterized by an increased expression of fibroblast growth factor 1 and fibroblast growth factor receptor 2 compared to BRCA1-associated breast tumors." (PMID 31244284, 2019).
hepatocellular carcinoma (5 papers, 2012 to 2023). A malignant tumor that arises from hepatocytes. "In hepatocellular carcinoma cells, miR‐143‐3p was found to inhibit proliferation and invasion by regulating its target gene, FGF1." (PMID 36708044, 2023). "And FGF1 induced FGFR phosphorylation to activate PI3K and JNK, resulting in the activation of MMP7 and MMP6 in hepatocellular carcinoma, which might be the underlying mechanism in the hepatocellular carcinoma metastasis." (PMID 26183397, 2015).
osteoarthritis (5 papers, 2021 to 2025). A noninflammatory degenerative joint disease occurring chiefly in older persons, characterized by degeneration of the articular cartilage, hypertrophy of bone at the margins and changes in the synovial membrane. "Studies in mice have shown that FGF1 knockdown can reduce cartilage damage in osteoarthritis." (PMID 39684926, 2024). "It results to the point that the novel usage of FGFR1-bound EV-derived MSC could be beneficial in the treatment of osteoarthritis by preventing ligation of FGF1 to the natural FGFR1." (PMID 35836973, 2022). "FGF1 gene is expressed in chondrocytes from articular cartilage of osteoarthritis patients." (PMID 34611583, 2021). "Moreover, Fgf21, shown to alleviate senescence, apoptosis, and ECM degradation in osteoarthritis via the SIRT1‐mTOR signaling pathway, was upregulated in the agarose encased cells, together with Fgf1 and 2, markers of human fetal growth plate cartilage, and Fgfr3, a key regulator of chondrogenesis." (PMID 40415244, 2025).
ulcer (5 papers, 2013 to 2022). "FGF-1 can significantly increase the number of capillaries and fibroblasts in ulcer tissue, and enhance the expression of transforming growth factor-β and nuclear antigen proliferating protein (PCNA), thus improving diabetic ulcer tissue." (PMID 34721299, 2021). "Fibroblast growth factor-1 (FGF1) showed only a slight benefit in multiple studies regarding increasing complete ulcer healing rates and incidence while reducing ulcer size and time to complete ulcer healing, with a few studies showing no statistical difference from placebo." (PMID 36035037, 2022).
deep vein thrombosis (4 papers, 2023 to 2025). "FGF1 is also cardioprotective (anti-thrombotic), and blocking FGF1 synthesis by activating FGF1 promoter methylation exacerbated deep vein thrombosis." (PMID 40277942, 2025). "FGF1 is shown to be cardioprotective (anti-thrombotic) and blocking FGF1 synthesis by activating FGF1 promoter methylation exacerbated deep vein thrombosis." (PMID 39199276, 2024). "Recently, Zhang and Qin demonstrated that in patients with lower extremity deep vein thrombosis, lncRNA LINC00659 facilitated the DNMT3A-mediated methylation of the fibroblast growth factor 1 (FGF1) promotor, which inhibited the proliferation and angiogenesis ability of endothelial progenitor cells." (PMID 37947606, 2023).
liver disease (4 papers, 2019 to 2026). "Through the inhibition of oxidative stress, fibroblast growth factor 1 (FGF1) is an effect therapy for a variety of liver diseases, but its use is limited by an increased risk of tumorigenesis due to hyperproliferation." (PMID 36110535, 2022). "Because FGF1 can promote the differentiation and maturation of liver-derived stem cells, it has been extensively studied for its therapeutic benefits in liver diseases based on the inhibition of oxidative stress." (PMID 36110535, 2022). "Fibroblast growth factor 1 (FGF1) showed protective potential in various liver diseases, but the role of endogenous FGF1 in DOX-induced liver damage is currently unknown." (PMID 37999577, 2023). "Indeed, accumulating evidence indicates that FGF1 is involved in various liver diseases." (PMID 37999577, 2023).
myocardial ischemia (4 papers, 2019 to 2023). A disorder of cardiac function caused by insufficient blood flow to the muscle tissue of the heart. "FGF1 can promote the proliferation of vascular endothelial cells and smooth muscle cells, thereby promoting angiogenesis, alleviating myocardial ischemia, and improving cardiac function." (PMID 31998132, 2019). "In previous studies, in various animal models of myocardial ischemia or infarction, FGF1 increased the regional myocardial blood flow and the density of capillaries and arterioles and improved ventricular function." (PMID 31998132, 2019). "PI3K/AKT is also one of the pathways activated by fibroblast growth factor-1 (FGF-1), which, in combination with the inhibition of p38 kinase (a known negative regulator of the cell cycle), increases mitotic events in mice and rats, improving heart function after myocardial ischemia." (PMID 37030487, 2023).
nonalcoholic fatty liver disease (4 papers, 2019 to 2024). "FGF-1 could effectively alleviate liver inflammation in a mouse model of nonalcoholic fatty liver disease." (PMID 34281287, 2021). "In addition, this corresponded to the anti-inflammatory effects of FGF-1 with respect to its ability to significantly prevent the development of nonalcoholic fatty liver disease (NAFLD) and diabetic nephropathy (DN)." (PMID 31866871, 2019).
renal fibrosis (4 papers, 2018 to 2022). A final common manifestation of a wide variety of chronic kidney diseases characterized by glomerulosclerosis and tubulointerstitial fibrosis. "For instance, miR-181a acts as a pro-fibrotic miRNA by promoting renal fibrosis through the targeting of fibroblast growth factor 1 (FGF1)." (PMID 35890132, 2022). "In present study, we had further confirmed the protective role of FGF1 on DN with attenuation of renal fibrosis and glomerulosclerosis." (PMID 30320493, 2018).
serous ovarian cancer (4 papers, 2018 to 2024). "Another study found significant differences between FGF1 mRNA level and overall survival in 42 patients with advanced stage high-grade serous ovarian carcinoma, suggesting that FGF1 amplification may be a poor prognostic factor." (PMID 38273381, 2024). "Overexpression of Fibroblast Growth Factor 1 (FGF1) is observed in various cancers, correlates with poor survival and could be responsible for resistance to platinum-based chemotherapy of serous ovarian cancers." (PMID 29467390, 2018).
spinal cord injury (4 papers, 2018 to 2024). Penetrating and non-penetrating injuries to the spinal cord resulting from traumatic external forces (e.g., WOUNDS, GUNSHOT; WHIPLASH INJURIES; etc.). "Fibroblast growth factor 1 (FGF1) is thought to exert protective and regenerative effects on neurons following spinal cord injury (SCI), although the mechanism of these effects is not well understood." (PMID 29512938, 2018).
colon carcinoma (3 papers, 2011 to 2021). "To test if R50E may act as an antagonist to FGF signaling in vivo, we stably expressed R50E or WT FGF1 in a secretion vector in DLD-1 colon carcinoma cells, and tested if R50E affects tumor growth in vivo." (PMID 23469107, 2013). "For instance, FGF1 and FGF2 have been shown to promote migration of intestinal epithelial cells, and specific isoforms of FGFR3 can mediate growth and migration of colon cancer cells." (PMID 21853123, 2011).
COVID-19 (3 papers, 2020 to 2025). A disease caused by infection with severe acute respiratory syndrome coronavirus 2. "The lack of modulation of this gene may represent a favourable aspect concerning long-term COVID-19, as the increased expression of FGF-1 is associated with various metabolic defects and tumorigenesis." (PMID 40709999, 2025). "One study, involving 210 patients diagnosed with COVID-19 and 80 healthy individuals, evaluated the plasma concentrations of several vascular factors, including FGF-1." (PMID 40709999, 2025). "This study has shown that the blood levels of GH, FGF-1, BDNF, and PDGF are reduced after six months of COVID-19, and the reductions persist after fifteen months of recovery." (PMID 40709999, 2025). "Seven common DEGs (PPARGC1A, FUBP1, ITGB8, SYCP2, RSAD2, FGF1, and FERMT1) were identified from the GSE164805 dataset of patients with mild COVID-19, and the GSE50395 dataset from APS patients." (PMID 36241659, 2022). "After six months of infection, patients with severe COVID-19 presented reduced PDGF and TGF-β, as compared with controls, whereas the levels of FGF-1 were not different." (PMID 40709999, 2025).
diabetic foot ulcers (3 papers, 2012 to 2024). "FGF1, FGF2, FGF4, FGF7, FGF16, FGF21, and FGF23 have been found to have good therapeutic outcomes for diabetic foot ulcers." (PMID 34831463, 2021).
epilepsy (3 papers, 2013 to 2021). A brain disorder characterized by episodes of abnormally increased neuronal discharge resulting in transient episodes of sensory or motor neurological dysfunction, or psychic dysfunction. "FGF1 has also been linked to a role in an animal model of epilepsy." (PMID 34301297, 2021). "Contrary to this, FGF1 has been shown to have anti-convulsant properties in kainate-induced epilepsy." (PMID 34301297, 2021). "However, the role in epilepsy of neurogenesis (and, based on these studies, of FGF1) is still uncertain." (PMID 24062643, 2013). "FGF1 (also known as acidic FGF, aFGF) has been reported to be implicated in rodent models of epilepsy but, to date, it has not been studied in the human disease." (PMID 24062643, 2013).
Hypertension (3 papers, 2013 to 2019). The presence of chronic increased pressure in the systemic arterial system. "According to the inference, genistein binds to the FGF1 protein in fibroblasts of the skin; the FGF1 protein activates the FGFR1 protein in the muscle cells of the heart; FGFR1 protein activates the UBC protein; the UBC protein activates the CTGF protein, and CTGF affects hypertension." (PMID 31138123, 2019).
ischemia (3 papers, 2012 to 2021). A hypoperfusion of the BLOOD through an organ or tissue caused by a PATHOLOGIC CONSTRICTION or obstruction of its BLOOD VESSELS, or an absence of BLOOD CIRCULATION. "Although FGF1 transgenic mice had a normal phenotype with unperturbed kidney structure, they showed a severely inhibited kidney repair after unilateral ischemia/reperfusion." (PMID 22606265, 2012). "Alternatively, ischemia may induce the leakiness of the endothelial monolayer and thus diffusion of FGF1 released from the apical surface of EC to the exposed areas of the basal membrane." (PMID 22606265, 2012). "The presence of numerous proliferating cells in the interstitium of postischemic kidneys of FGF1/Tek mice supports the hypothesis that ischemia stimulates FGF1 export from EC to surrounding structures." (PMID 22606265, 2012). "Another advantage of our in vivo model was that despite permanent FGF1 expression in EC, transgenic animals exhibited a normal phenotype, including unperturbed kidney structure; therefore, we were able to specifically focus on FGF-dependent events caused by ischemia and postischemic stress." (PMID 22606265, 2012). "However, our study model was restricted to normal physiological conditions, and more experiments are required to understand whether FGF1 will have any antiarrhythmic effect under more complex pathological conditions (such as Ca2+ overload, oxidative stress, or ischemia)." (PMID 35118146, 2021).
ischemic disease (3 papers, 2012 to 2014). Lack of blood supply to an area of the body, resulting in impairment of tissue oxygenation. "The low intrinsic stability of FGF-1 has been identified as one of the key challenges in the development of FGF-1 as a successful pro-angiogenic drug candidate for the treatment of ischemic diseases and wound healing." (PMID 24659968, 2014). "Fibroblast growth factor-1 (FGF-1) is an angiogenic factor with therapeutic potential for the treatment of ischemic disease." (PMID 23133616, 2012).
ischemic stroke (3 papers, 2020 to 2024). A stroke disorder caused by obstruction of blood flow to the brain, due to thrombotic (local blood clot formation) or embolic (due to a blood clot or other material traveling from another site) event. "Previous studies have demonstrated that FGF1 could induce neurogenesis and angiogenesis in rats after ischemic stroke and rescue hippocampal neurons from apoptotic death induced by ischemia." (PMID 32194396, 2020).
pancreatic adenocarcinoma (3 papers, 2001 to 2025). "Our findings of the highest level of HSPGs with the use of FGF1HSBCD biosensor present in pancreatic carcer cell line support previous reports on increased level of HSPGs in pancreatic adenocarcinoma cells and highlight the feasibility of the developed FGF1 variant as HS/HSPG sensor." (PMID 40437501, 2025). "In pancreatic adenocarcinoma, FGF-1 and FGF2 have been shown to up-regulate E-cadherin expression." (PMID 23554977, 2013). "We have investigated the effects of FGF-1 and FGF-2 on the behaviour and adhesion properties of human pancreatic adenocarcinoma cell lines (BxPc3, T3M4 and HPAF) that were previously characterised for the expression of FGFRs." (PMID 11401320, 2001).
rheumatoid arthritis (3 papers, 2015 to 2020). A chronic, systemic autoimmune disorder characterized by inflammation in the synovial membranes and articular surfaces. "As early as 1990, a T-cell-dependent increase in FGF-1 expression was described in the inflamed joints of patients with rheumatoid arthritis, and it was directly correlated with the extent and intensity of inflammation." (PMID 25638171, 2015).
Stroke (3 papers, 2020 to 2022). Sudden impairment of blood flow to a part of the brain due to occlusion or rupture of an artery to the brain. "Stroke-prone spontaneously hypertensive rat studies showed that β-carotene decreased fibroblast growth factor-1 (FGF1)-mediated gliosis of astrocytes by increasing the expression of genes related to cholesterol regulation: Abcg2, Abca1, Hmgcr, and Apoe." (PMID 34360658, 2021). "Previous studies have shown that the intranasal administration of FGF1 could enhance angiogenesis after stroke." (PMID 32194396, 2020). "For the safe application of FGF1, we applied nmFGF1 to mice after stroke and HBMECs after OGD/R." (PMID 32194396, 2020). "Demethylation by TET1, TET3, and Gadd45b controls the expression of galanin, Ng2, bdnf, fgf-1, RAG, and Bdnf IV in the neurorepair mechanism in stroke." (PMID 36142283, 2022).
thyroid cancer (3 papers, 2015 to 2022). "Extrapolating these findings to thyroid cancer implicates S100A13 as a new oncogenic factor in PTC, and this could warrant evaluation of the effectiveness of inhibiting S100A13-driven release of FGF-1." (PMID 25880590, 2015).
Arthritis (2 papers, 2021 to 2025). Inflammation of a joint. "FGF1 was also associated with the development and progression of arthritis." (PMID 35010640, 2021).
blepharitis (2 papers, 2021 to 2024). Inflammation of the eyelids near the eyelashes. "For example, treatment with an engineered FGF1 reduced the severity of keratitis and blepharitis in HSV-1 infected mouse cornea without affecting viral replication, possibly because of the repair-promoting effect of FGF1." (PMID 39621133, 2024).
Brain atrophy (2 papers, 2005 to 2017). Partial or complete wasting (loss) of brain tissue that was once present. "The absence of intact FGF1 in the S10 mice could be critical in the age-related neurodegeneration and brain atrophy observed in the S10 strain." (PMID 15960800, 2005).